INS (insulin)
Diseases named in the same sentence as INS in open-access papers (continued):
Sharing a sentence is not in itself a finding about the gene and the disease.
asthma (continued). "Insulin causes a hypercontractile phenotype of bovine ASM, similar to that seen in asthma, by increasing the production of b1-containing laminins through a phosphoinositide-3 kinase (PI-3K)/Akt-dependent signaling pathway." (PMID 38398039, 2024). "In this context, the purpose of this review was to summarize current data on the deleterious role of insulin resistance in asthma, along with suggested mechanisms of asthma irritation." (PMID 38398039, 2024). "Regarding other medication use, 19% of the retired rugby players reported using allergy medication, 10% reported using asthma medication, and only one participant reported using insulin." (PMID 39355554, 2024). "Accordingly, insulin is important in the pathogenesis of apoptosis-driven lung diseases (such as asthma and chronic obstructive pulmonary disease)." (PMID 38398039, 2024). "PPARγ, which has been extensively studied in the field of lipid metabolism and insulin signaling, also plays a crucial role in allergic diseases such as asthma." (PMID 38030614, 2023). "In contrast, insulin was discovered to raise the incidence of asthma in diabetic patients in the same study." (PMID 37056543, 2023). "A study states that excess insulin can directly affect lung cellular physiology, which provides a clue of a similar molecular mechanism between asthma and cardiometabolic syndrome." (PMID 37362491, 2023). "High-frequency keywords related to respiratory delivery include nanoparticles, BBB, chitosan, insulin, asthma, and COPD, which are relevant to the two drug delivery methods." (PMID 36145722, 2022). "That result is thereby very interesting since it was published shortly after a study carried out on mice in which it was shown that insulin administered intranasally produced bronchial hyperreactivity and increased the depositing of collagen in the lungs." (PMID 34836093, 2021). "Almost half of the women had a chronic disease, 6 had gestational complications and 7 took medication during pregnancy (analgesics, antibiotics, cobalamin, asthma medication and insulin)." (PMID 32492052, 2020). "Prevalence of deprivation, smoking, substance or alcohol misuse, prescription of insulin and AEDs was higher amongst women prescribed asthma medicines, with the exception of those prescribed ICS or ICS only." (PMID 33296383, 2020). "Two confirmatory testing panels were used—the primary panel was betaxolol-glucagon (children ≥15 kg) or glucagon (<15 kg or asthma), and the secondary was arginine-insulin (children ≥15 kg) or arginine (children <15 kg)." (PMID 33324312, 2020). "Of the 14 patients given an insulin pump, eight had other atopic manifestations or drug allergy (challenge-verified penicillin allergy, atopic dermatitis, asthma, hay fever, contact allergy, and urticaria)." (PMID 30258565, 2018). "In a similar model of asthma, insulin was shown to modulate the production of cytokines, such as TNF-α and IL-1β, along with expression of adhesion molecules (P- and E-selectins) and neutrophil migration into the lungs." (PMID 28649241, 2017). "The results suggest that insulin modulates the production/release of cytokines, cell migration, deposition of collagen, and mucus secretion in lung remodeling of a mouse model of asthma." (PMID 28649241, 2017). "This study aimed to evaluate the role of insulin in lung remodeling of a model of asthma in healthy and diabetic mice." (PMID 28649241, 2017). "The role of insulin in lung remodeling in a model of asthma in healthy and diabetic mice was evaluated." (PMID 28649241, 2017). "Treatment with resveratrol reestablished the insulin signaling pathway in the lungs of obese mice, placing this compound as a putative pharmacological strategy aiming to reduce the asthma exacerbations in obese individuals." (PMID 29229986, 2017). "Treatment of these animals with insulin ameliorated this condition, suggesting that asthma symptoms are suppressed by the diabetic state." (PMID 28649241, 2017).
asthma (continued). "Enzyme PKC-a has been proposed to be involved in asthma pathogenesis, in adipogenesis and lipid mediated insulin resistance." (PMID 27411394, 2016). "We observed an increased risk of developing TB infection in older males with a history of asthma, users of diuretics, isosorbide, acarbose and insulin-based therapies such as meglitinides and insulin." (PMID 25993300, 2015). "Huckvale and colleagues conducted systematic assessments of smartphone apps for calculating insulin dosage, educating patients about asthma, and the privacy characteristics of “accredited” apps in the National Health Service (NHS) Health Apps Library." (PMID 26404791, 2015). "Certainly, insulin can shift T cells towards a Th2-type response, known to be a key event in the pathogenesis of asthma." (PMID 24204385, 2013). "If insulin excess can directly alter lung cellular physiology, this would represent a fundamental common molecular link between asthma and the cardiometabolic syndrome." (PMID 24204385, 2013). "While not a direct report of GATA-3 findings, it emphasizes the integration of comprehensive metabolic profiling—including insulin sensitivity and body composition—alongside traditional inflammatory and respiratory metrics in randomized controlled asthma trials." (PMID 41567689, 2026). "Among the various mechanisms by which insulin may alter the development or severity of asthma, its adverse effect on airway contractility has been widely reported." (PMID 39371928, 2024). "Indeed, studies carried out in a mouse model showed that insulin sensitizers can be effective in the treatment of asthma." (PMID 37108123, 2023). "Additionally, it was discovered that the occurrence of asthma was 1.02 times higher in people with higher insulin levels (95% CI 1.01-1.04; p = 0.015)." (PMID 37056543, 2023). "Given that insulin levels also vary during the menstrual cycle, it has been hypothesized that insulin resistance may play a central role in asthma exacerbation." (PMID 37108123, 2023). "In keeping with these effects of insulin on ASM, treatment with anti-diabetic medications, including metformin, a biguanide, and albiglutide, a glucagon-like peptide-1 receptor (GLP-1R) agonist, have been associated with decreased asthma disease burden." (PMID 36837831, 2023). "Recent human birth cohort studies have shown that higher blood insulin in early childhood is associated with a later increased asthma risk and reduced lung function in adulthood, independent of BMI." (PMID 36107629, 2022). "When we stratified the CRD into parenchymal lung lesions (including lung cancer and TB) and airway disease (including COPD, tracheitis/bronchitis, and asthma), we found that both parenchymal lung lesions and airway disease had higher insulin use ratios (40.20%, 28.52%, all p’s <.0001, respectively)." (PMID 36093107, 2022). "One instance could be the more effective delivery of inhaled drugs to the lung airway; e.g., an asthma inhaler or dry powder insulin inhaler." (PMID 31323757, 2019). "Insulin treatment restored this condition, suggesting a major role of insulin in asthma." (PMID 28649241, 2017). "Cyclic ADPR is an important intracellular second messenger that participates in Ca2+ mobilization and it is involved in regulating multiple physiological functions and pathogenesis including fertilization, T-cell activation, chemotaxis, insulin secretion, and airway constriction and asthma." (PMID 27547294, 2016). "On apps, patients are not only getting health information, but also logging their weight, fitness activity, asthma peak flow numbers, insulin levels, food intake, and more, moving patients and families from passive recipients of information to active participants in their health and health care." (PMID 28007689, 2016).
asthma (continued). "Adiponectin is an adipokine with insulin-sensitizing and anti-inflammatory effects, and low level of adiponectin has been associated with both incident asthma and metabolic disorders, even though the association has not been consistent." (PMID 27212806, 2016). "In three systematic assessments published in BMC Medicine, Huckvale and colleagues demonstrate that widely available health apps meant to help patients calculate their appropriate insulin dosage, educate themselves about asthma, or perform other important functions are methodologically weak." (PMID 26404791, 2015). "Insulin concentrations need to be increased beyond these concentrations by 3 to 4 times to induce an anti-inflammatory effect, be it the suppression of NFκB or other inflammatory factors like chemokines or asthma related genes." (PMID 25642424, 2015). "Insulin suppresses the expression of these genes and mediators related to asthma and may, therefore, have a potential role in the treatment of asthma." (PMID 25642424, 2015). "Nonetheless, considerable insight into potential mechanisms by which insulin influences lung cellular components relevant to asthma may be gleaned from such prior data." (PMID 24204385, 2013). "However, the insulin doses used by individuals with concomitant asthma and T1DM were higher." (PMID 38331806, 2024). "A study showed that treatment with inhaled insulin was responsible for increased airway hyperresponsiveness, human smooth muscle proliferation, collagen deposition, and peri-bronchial thickening (p < 0.05), which are similar to the pulmonary findings in asthma." (PMID 37056543, 2023). "Therefore, it is reasonable to assume that the amelioration of asthma exacerbations in insulin resistant obese mice by resveratrol may be due to restoration of the insulin signaling pathway in the lungs." (PMID 29229986, 2017). "The proposed mechanisms how asthma could increase the risk for DM2 include genetic pleiotropy, lung-related inflammatory cytokines and their effects on insulin sensitivity, direct effects of hypoxia on glucose metabolism, and adverse early-life exposures and their effects on organ development." (PMID 27212806, 2016). "In asthma, mitochondrial damage impairs airway cell repair, while in T1DM, it compromises insulin secretion and beta-cell survival." (PMID 40004164, 2025). "Several retrospective observational cohorts have shown a link between the use of insulin in T2DM and the onset of asthma." (PMID 39272654, 2024). "Similar trends for reduced risk of the composite respiratory endpoint were observed among SGLT2i users in each age, sex, and history of asthma, history of COPD, history of CVD, history of CKD, and history of baseline insulin use subgroup." (PMID 36765407, 2023). "However, multiple doses of insulin restored the deposition of mucus and collagen in the airways, which suggests that appropriate treatment with insulin may modulate cytokine levels, cell migration, eosinophilia, and mucus and collagen deposition in lung remodeling in the murine asthma model." (PMID 28649241, 2017). "Insulin reduced short-term activation of NF-κB and expression of many inflammatory mediators (IL-4, ADAM-33, LIGHT, and LTBR) related to asthma in these cells." (PMID 27212806, 2016). "Insulin decreased mRNA expression of IL-4, ADAM-33, and LTBR (lymphotoxin beta receptor), which are all potentially involved in pathogenesis of asthma." (PMID 26783384, 2015). "As a growth factor, the contribution of insulin to increased ASM mass and/or contractility in the context of asthma is obviously important." (PMID 24204385, 2013). "No significant changes in mean 25(OH)D levels were observed in patients taking NSAIDs, vitamin K antagonists, inhalers for asthma/COPD, ezetimibe, thiazide and loop diuretics, corticosteroids, serotonin reuptake inhibitors, angiotensin II antagonists, or insulin." (PMID 41304971, 2025).
asthma (continued). "For instance, the SHAP values of Insulin signaling pathway (a sex-shared pathway) appeared negative in most males and females of the control group, whereas the asthma group showed positive values." (PMID 38807262, 2024). "However, patients with asthma and T1DM needed higher doses of insulin for reaching a good glycemic control." (PMID 38331806, 2024). "According to another study, children with asthma are more likely to have higher levels of blood insulin and triglycerides than those without asthma." (PMID 36833618, 2023). "Unlike the medications for asthma treatment, inhaled insulin utilizes the alveoli more than the rest of the respiratory tract for absorption." (PMID 32850233, 2020). "By the fact that insulin infusion suppresses the expression of IL-4, ADAM-33, LIGHT, and LTBR and the plasma concentrations of NOM and MMP-9, the efficacy of insulin in the treatment of asthma needs to be assessed." (PMID 25642424, 2015). "Since 2011, asthma apps have become more interactive, but have not improved in quality; peak flow calculators have the same issues as the insulin calculators." (PMID 26404791, 2015). "Then those who without information on fasting glucose (n = 1330), insulin (n = 17), serum total IgE/allergen-specific IgE (n = 10), allergy (n = 2), asthma (n = 1), height (n = 1), SBP (n = 27), energy intake (n = 26), cotinine (n = 3) or VD (n = 1) were excluded." (PMID 38745118, 2024). "There is one inhaled insulin currently available, used for mealtime boluses; it does not remove the need for subcutaneous injection if basal insulin is needed, however, and is contraindicated in patients with asthma or chronic lung disease." (PMID 34184589, 2021). "It is possible to speculate that asthma is suppressed in type I diabetic individuals because there is a relative lack of insulin which, in turn, would allow asthma to manifest itself clinically." (PMID 32117245, 2020). "Overall, the data so far suggests that, if anything, insulin effects on ASM are likely to result in increased airway contractility, cell proliferation, and fibrosis, all of which should lead to a thicker, stiffer, and hypercontractile airway reflective of an asthma phenotype." (PMID 24204385, 2013). "While insulin is not currently thought of as a major player in asthma pathogenesis, there are well-established effects of insulin on airway smooth muscle and fibroblasts in animal models that may promote bronchoconstriction and remodeling." (PMID 24294267, 2013). "It is possible to speculate that asthma is suppressed in diabetic individuals because there is a relative lack of insulin which, in turn, would allow asthma to manifest itself clinically." (PMID 20667094, 2010). "With regard to glucose metabolism, the FPG concentration, fasting insulin concentration, and HOMA index were higher in patients with asthma than those without asthma (P = 0.0103, P < 0.0001, and P < 0.0001, respectively)." (PMID 31192262, 2019). "The FPG concentration, fasting immunoreactive insulin concentration, and HOMA index were higher in patients with asthma than those without asthma (P < 0.05, P < 0.0001, and P < 0.0001, respectively)." (PMID 31192262, 2019). "Furthermore, in a prospective cohort study involving patients with type 2 DM without existing asthma or COPD (chronic obstructive pulmonary disease), the commencement of insulin therapy increased airway reactivity within the initial 60 days." (PMID 39272654, 2024).
Infertility (154 papers, 2005 to 2026). "While current treatments focus on symptom relief through hormone regulation, insulin sensitizers, or ovulation induction, there is a need to target the underlying molecular and cellular processes that drive disease progression and infertility." (PMID 42193977, 2026). "Patients with IR should be advised to improve insulin sensitivity through intervention before infertility treatment to reduce the risk of spontaneous abortion." (PMID 40441206, 2025). "GLP-1 RAs facilitate weight loss, enhance insulin sensitivity, reduce systemic inflammation, and regulate menstrual cycles to treat infertility." (PMID 39677183, 2024). "Our study has yielded pivotal insights into the complex relationship between insulin signaling and endometrial function, particularly in the context of infertility associated with Polycystic PCOS." (PMID 38310251, 2024). "In this MR analysis, genetic instruments suggested that higher concentrations of fasting insulin increase the risk of infertility in women." (PMID 37949105, 2024). "In women, increases in genetically determined fasting insulin levels were associated with greater odds of infertility (+1 log(pmol/l): odds ratio 1.60, 95% CI 1.17 to 2.18, P-value = 0.003)." (PMID 37949105, 2024). "Other less invasive options, such as the use of insulin sensitizers like metformin or thiazolidinediones, are proven to be beneficial for weight loss and the treatment of infertility in women with PCOS." (PMID 36675355, 2023). "This study showed that lifestyle interventions preceding infertility treatment resulted in substantial weight loss and slight improvement in IR, whereas metformin intervention improved insulin sensitivity and had a modest impact on weight loss." (PMID 37700375, 2023). "Genetic manipulation of insulin signaling has the most dramatic effect on lipid mobilization from the fat body, with loss of insulin signaling leading to poor growth, runtiness, infertility, and longevity in certain cases." (PMID 18081423, 2007). "In line with the observed muscle mass differences, the larger waist and hip circumference in infertile women may indicate fat distribution patterns associated with insulin resistance and hormonal imbalances." (PMID 39444570, 2024). "On the one hand, high insulin level directly acts on ovarian thecal cells through insulin receptor, causing excessive functional androgens; On the other hand, high insulin level disrupts the normal function of the hypothalamus-pituitary-ovary gonadal axis, which ultimately cause infertility." (PMID 37461021, 2023). "Consumption of low-fat and skimmed milk can be associated with higher levels of insulin and insulin-like growth factor-1 and thus spermatogenesis, while the reason for the adverse effect of high-fat dairy on infertility can be ascribed to the high content of SFA." (PMID 35911859, 2022). "Through insulin resistance (IR) and high levels of insulin and androgens, the adipose tissue is responsible for ovulatory disorders in disposed patients and the anovulation associated to obesity is responsible for higher risk of miscarriages and infertility." (PMID 31231310, 2019). "And to our best knowledge, this trial is the first study assessing the effects of vitamin D supplementation on glycemic control, markers of cardiometabolic risk and gene expression of insulin and lipid metabolism in infertile women diagnosed with PCOS who were candidate for IVF." (PMID 30286768, 2018). "Treatments for lower fasting insulin levels may reduce the risk of infertility in women." (PMID 37949105, 2024). "Furthermore, defects in insulin/IGF1 signaling can cause infertility." (PMID 36506051, 2022). "Therefore, we can suggest that lean body mass could be implicated in infertility since it plays an important role in the control of systemic energy metabolism and insulin sensitivity —both of which interfere with fertility." (PMID 31017887, 2019).